SMAD3 (SMAD family member 3)
Diseases named in the same sentence as SMAD3 in open-access papers (continued):
Sharing a sentence is not in itself a finding about the gene and the disease.
tumor (continued). "Using the TCGA data from colon, rectal, gastric cancer patients and their own results of the Illumina Methylation 450K BeadChip array analysis of a CRC patient tumor and normal tissues, the authors selected EHD3, TMEM240, and SMAD3 as promising tumor markers." (PMID 37569782, 2023). "TGF-β/SMAD3 signaling pathway plays a critical role in inhibiting tumor formation by suppressing cell growth and promoting apoptosis, both in normal cells and during the early stages of tumorigenesis." (PMID 37941785, 2023). "Trastuzumab, a monoclonal, anti-human ERBB2 protein antibody, inhibits tumor size and metastasis in vivo and in vitro through the upregulation of β-catenin and inhibition of SMAD3." (PMID 37174100, 2023). "Moreover, our results support that the tumour-promoting effects associated with the enhanced migration of high SMAD3 fibroblasts could be prevented with Trametinib or other MEK inhibitors in ADC but not SCC, since high SMAD2 fibroblasts as in SCC-TAFs were largely non-responsive to MEK inhibition." (PMID 36572730, 2023). "Inha/Smad3 double KO mice have reduced tumour frequency and size, confirming that elevated activin signalling via SMAD3 drives tumour formation." (PMID 37564373, 2023). "We previously showed that Smad3-KO mice exhibit a profound reduction in tumor growth using the LLC and B16F10 cancer cell lines." (PMID 37002229, 2023). "Here we demonstrate that TGF-β/Smad3 signaling also promotes tumor growth by promoting a protumor N2 state in TANs." (PMID 37002229, 2023). "By contrast, re-expression of AR and AR-V7 in the SMAD3-KD Rv1 cells partially restored the frequency and size of xenograft tumor formation." (PMID 36727462, 2023). "We found that ectopic expression of Smad3 reversed the inhibitory effect of docetaxel on tumor glycolysis and cell proliferation." (PMID 36536346, 2022). "In NSCLC, TGF-β signaling is frequently enhanced and promotes EMT and tumor metastasis, whereas SMAD3 inhibition diminished TGF-β-induced EMT in cancer cells." (PMID 35291909, 2022). "TGF-β secreted by tumor cells binds to and activates receptors on the precursors of CAFs, resulting in the phosphorylation of Smad2 and Smad3." (PMID 36109762, 2022). "In conclusion, this work reveals that SMAD4 inactivation in PDAC not only results in a loss of SMAD4 tumor suppressive function but is concomitant to the oncogenic gain-of-function of SMAD2 and SMAD3." (PMID 36207615, 2022). "The activation of TGF-β and Smad3 is essential for the tumor-induced formation of CD45− EPCs in the spleen (also known as Ter cells)." (PMID 36567722, 2022). "What’s more, Smad3 also has been reported to play a critical role in metabolic reprogramme in tumor progression, including tumor glycolysis, glutaminolysis, lipid metabolism." (PMID 36536346, 2022). "In concordance, we finally demonstrated that genetic and pharmaceutic targeting of Smad3 effectively blocks MNT-driven tumor innervation in mice." (PMID 36206343, 2022). "Herein, we presented a case of EWSR1::SMAD3-rearranged fibroblastic tumor that recurred twice in a 20-year-old man." (PMID 36591513, 2022). "Instead, tumors displayed inconsistent patterns of changes, with decreased expression of tumor cell p-SMAD2, p-SMAD3, and p21 in 4 (29%), 7 (50%), and 5 (37%) samples, respectively, and an increase in tumor cell Ki67 expression in 5 (37%) samples." (PMID 35727629, 2022). "SE hijacking LINC01977 promote TGF-β/SMAD3-mediated crosstalk between the intrinsic characteristics of cancer and the extrinsic characteristics of the tumor microenvironment." (PMID 35982471, 2022).
tumor (continued). "The present study further characterizes the mechanisms involved in hypoxia-induced cancer cell invasion using in vitro, in vivo and in silico approaches and identifies a HDAC6- SMAD3 pathway that can be pharmacologically targeted to inhibit tumor progression." (PMID 35681731, 2022). "EWSR1::SMAD3-rearranged fibroblastic tumor is a recently described entity that mostly occurs in acral locations." (PMID 36591513, 2022). "This context-dependent expression of SMAD3 fits well with its established dual role as a tumor suppressor in early cancer and a tumor promoter in late-stage tumors in which it supports invasion and metastasis." (PMID 35565214, 2022). "We have previously demonstrated that the combination treatment of AA and NG can effectively rebalance the Smad3 and Smad7 signaling in the acute kidney injury model 9 and tumor microenvironment." (PMID 36147472, 2022). "More precisely, we demonstrated that the tumor suppressive function of SMAD2 remained intact while the pro-invasive role of SMAD3 was exacerbated under hypoxic conditions." (PMID 35681731, 2022). "In the present study, we found that GDF10 also promotes the growth and migration of OSCC tumor cells by activating the TGFβRI/Smad3/ERK pathway." (PMID 33657265, 2022). "The interaction of GDF10 with the transcription factor RUNX family transcription factor 2 further enhanced the growth and migration of OSCC tumor cells by activating the TGFβRI/Smad3/ERK pathway." (PMID 33657265, 2022). "Smad3 regulates the metastasis of tumor cells and the expression of epithelial–mesenchymal–transition genes." (PMID 36387210, 2022). "In nude mice xenograft model, AMTB treatment augmented tumor cells’ sensitivity to cisplatin, by smodering Smad2 and Smad3 phosphorylation and, therefore, repressing the activation of TGFβ signaling, which was implicated in tumorigenesis and tumor progression." (PMID 36844925, 2022). "As expected, knockdown expression of Smad3 significantly reduced DJ-1-induced migration and invasion of K150 and E109 cells in transwell and 3D tumor spheroid invasion assays." (PMID 36008860, 2022). "Increased exosomal SMAD family member 3 (SMAD3) in patients with HCC promotes lung metastases by enhancing circulating primary tumor adhesion." (PMID 35625364, 2022). "Taken together, our results indicate that EZH2 methylated SMAD3 at K53 and K333, triggering tumor metastasis." (PMID 35085106, 2022). "The results showed that SMAD3 K53/333R cells generated fewer metastatic nodules and lower tumor weights than did SMAD3 WT cells." (PMID 35085106, 2022). "Hypoxia-induced activation of the SMAD3 pathway through increased SMAD3 bioavailability and recruitment to the adapter protein SARA induced tumor progression and cancer cell invasion, events associated with the expression of SMAD3 gene targets ITGB2 and VIM." (PMID 35681731, 2022). "Overall, these findings further emphasize the SMAD2/3 dichotomy in tumor progression and suggest that SMAD3 expression is important for cancer cell invasion in response to hypoxia." (PMID 35681731, 2022). "SPTBN1 is a TGF-β signal-transducing adapter protein which is necessary for Smad3/Smad4 complex formation and functions as a tumor suppressor in many cancers." (PMID 35641855, 2022). "SMAD2 and SMAD3 mRNA levels are associated with nuclear and FIGO grades, and the SMAD4 mRNA level is significantly associated with tumor size, tumor subtype, lymphovascular invasion, nuclear and FIGO grade, and disease-free survival." (PMID 34501347, 2021). "In line with our notion, we detected a hyperactivation of Smad3 but inhibition of Smad7 in the primary HCC compared to the paired non‐tumour liver tissue." (PMID 34514726, 2021). "Combined predictive effect of SMAD3 tumor expression, SMAD3-rs745103 and SMAD3-rs744910 on tumor response." (PMID 35002714, 2021).
tumor (continued). "Therefore, similarly to IL-15, an altered SMAD-3 activity associated with specific genetic variants could modify the TGF-β-related transcriptional response impacting on both the tumor development and the antitumor FOLFIRI efficacy, finally affecting the patients’ prognosis." (PMID 33916844, 2021). "As the RNA seq analysis revealed constitutive TGFβ signaling in the tumor cells we investigated phosphorylation of Smad3 as indicator of pathway activation." (PMID 34290694, 2021). "Taken together, our data point to a connection between the expression of PLEXIND1 and SMADs2/3 and the involvement of SMAD3 in PLEXIND1-mediated tumor growth in the PANC-1 cell line." (PMID 34439202, 2021). "Combinatorial therapy achieved the most effective control of both mesenchymal and proneural tumors, although monotherapy alone targeted to Smad3 or HIF-1α hindered tumor growth near the detection limits." (PMID 34707087, 2021). "Consistently, Literatures have demonstrated that the SMAD3 and Erk pathways are also regulated by other factors in the tumor environment including steroid hormones and epidermal growth factor." (PMID 33602253, 2021). "Meanwhile, Western blots indicated that the combination treatment decreased the expressions of p-Smad3 and N-cadherin, increased the expression of E-cadherin, and reduced nuclear accumulation of Smad4 in tumor tissues." (PMID 34324434, 2021). "In HCC, tumor-derived sEVs were shown to transfer SMAD Family Member 3 (SMAD3) protein and mRNA to detached HCC cells and promote their homotypic adhesion." (PMID 34503190, 2021). "Taken together, these data suggest that LAE inhibited tumor metastasis, at least in part, via suppressing the phosphorylation of SMAD3 and Erk1/2." (PMID 33602253, 2021). "KAT6A directly binds to and acetylates SMAD3 at K20 and K117, which promotes SMAD3 association with oncogenic chromatin modifier TRIM24 and disrupts its interaction with tumor suppressor TRIM33." (PMID 34392614, 2021). "Next, we aimed to verify the H3K27ac signal of the TF SMAD3 in tumor samples by culturing eight kinds of malignant tumor cell lines." (PMID 34722892, 2021). "We injected the cells into the IL6−/− mice through tail vein injection to prevent confounding effects from the host IL‐6 and determined the impact of IL‐6 KO in SMAD3‐mediated tumor metastasis." (PMID 34392614, 2021). "In the early stage of tumor metastasis, many processes regulated by Erk, such as angiogenesis, are earlier than the SMAD3 pathway." (PMID 33602253, 2021). "Under the TGF-β signal transduction pathway, the SMAD2 and SMAD3 genes were found to be critical intracellular mediators, even reflecting tumor-inhibitory or tumor-inducing effects." (PMID 34579396, 2021). "This study addresses for the first time both the host and tumor component of SMAD3 profiling through a combined molecular approach." (PMID 35002714, 2021). "Patients who were part of the initial study group characterized for both SMAD3 tumor expression and SMAD3-rs745103 and rs744910 genotypes (74/76 patients) were considered for the combined analysis." (PMID 35002714, 2021). "Depending on the states of cancers, TGFβ/SMAD3 signaling can act as an oncogenic factor promoting the tumor cell invasion and metastasis in advanced cancers or functions as a regulator to inhibit cell proliferation and induce apoptosis in early-phase tumors." (PMID 34580281, 2021). "Taken together, these findings support the notion that SMAD3 has an important role in tumor metastasis and survival." (PMID 33758603, 2021). "We have recently identified a novel tumor-suppressive pathway, in which RAC1b-driven aTGF-β1 induces Smad3 expression in an exogenous TGF-β-independent manner." (PMID 33478130, 2021). "In contrast, tumour tissue showed increased staining of p‐Smad3 (Chi square, *P < .05) and TGF‐β1 (Chi square, **P < .01)." (PMID 33538080, 2021). "Our results demonstrate that in KRASmut PDAC cells, PLEXIND1 promotes tumor growth via SMAD3 signaling." (PMID 34439202, 2021).
tumor (continued). "SMAD3 functions as a transcriptional activator for inducing cytokine expression in the tumor microenvironment as well as an immunity repressor for enhancing MDSCs recruitment in driving cancer metastasis." (PMID 34392614, 2021). "It is worth to note that while silencing of either Smad2 or Smad3 led to accelerated c-Myc tumor growth, silencing of Smad4 demonstrated the most significant tumor acceleration phenotype." (PMID 33608500, 2021). "Overexpression of nuclear C-terminal phosphorylated SMAD3 (p-SMAD3) in preoperative tumor samples was indicated to identify LARC patients at higher risk for poor response to fluoropyrimidine-based nCRT." (PMID 35002714, 2021). "Treated with TGF-β and SB to analyze the interrelationship of TGFβ and Smad2 and Smad3 on tumor proliferation and metastasis." (PMID 34712379, 2021). "We found that the overexpression of Tipe2 in tumor cells markedly decreased the protein level of c-Myc, but increased the phosphorylation level of p-Smad3." (PMID 34702807, 2021). "Overall, our results revealed that EEF1A2 interacted with HSP90AB1 to activate SMAD3 signalling and promote tumour metastasis." (PMID 33473168, 2021). "In a group of 76 LARC patients, SMAD3 and phosphorylated-SMAD3 expression was assessed by immunohistochemistry in preoperative tumor tissue." (PMID 35002714, 2021). "The results in vivo showed that LAE inhibited tumor metastasis via suppressing the phosphorylation of SMAD3 and Erk1/2." (PMID 33602253, 2021). "Together, these results identified SMAD3 as an amenable target to limit resistance to BRAFi and tumor growth." (PMID 33724679, 2021). "Meanwhile, the combination treatment promoted anti-tumor mechanisms in Raji cells as indicated by decreases in p-Smad3 and N-cadherin and increases in E-cadherin." (PMID 34324434, 2021). "TGF-β stimulates neoangiogenesis by inducing VEGF expression in tumor and stromal cells like macrophages in a Smad3-dependent manner." (PMID 34712672, 2021). "Knockdown of SMAD3 inhibited tumor growth and promoted radiosensitivity of A549 cells in the mouse model." (PMID 32140069, 2020). "DNA methylation of SMAD3 was analyzed in 38 paired colorectal samples and 314 tumor sample datasets from TCGA." (PMID 33036415, 2020). "The expressions of p-Smad2 and p-Smad3 in tumor tissues were notably decreased by LINC01234 knockdown." (PMID 33178601, 2020). "Immunohistochemistry confirmed that the expression of SMAD3 was significantly decreased in knockdown of SMAD3 tumor tissues and p21 was significantly increased in overexpression p21 tumor tissues." (PMID 32140069, 2020). "OSM promotes epithelial to mesenchymal transition (EMT) of cancer stem cell (CSC) properties by activating Stat3/TGF-β/SMAD3 signaling, and therefore, promotes tumor metastasis and tumor recurrence." (PMID 33216732, 2020). "Intracellular IL-37b interacts with Smad3 to suppress multiple signaling pathways and the metastatic phenotype of tumor cells." (PMID 32226541, 2020). "SMAD3 mRNA expression was low in 42.9% of Taiwanese CRC tumor tissues but high in 29.4% of tumors compared with paired adjacent normal tissues." (PMID 33036415, 2020). "An online miRNA target prediction database (miRecords) showed that both Smad2 and Smad3, two well-known positive regulators of tumor metastasis, contained putative binding sites for miR-1258." (PMID 32372060, 2020). "Intriguingly, KD of SMAD3, but not SMAD2, in one model with stimulated metastasis (MVT1) increased metastasis, suggesting that SMAD3 has direct anti-metastatic effects on the tumor cell in this model." (PMID 33260366, 2020). "Quantitative real-time PCR (qRT-PCR) was conducted to detect the expression level of messenger RNA of ACTA2-AS1, miR-143-3p and SMAD3 in tumor tissues and cells." (PMID 32774166, 2020). "In the non-invasive tumor mass, TGF-β induces the association of SETDB1 with Smad3 to repress the expression of Snail through mediating H3K9 methylation in the promoter of Snail." (PMID 32114978, 2020).
tumor (continued). "Rigorously sticking to this concept allowed us to verify a hitherto unappreciated anti-migratory function for SMAD3 and autocrine TGFβ1, two factors that had before been considered classical tumor promoters." (PMID 33266416, 2020). "Regarding the methylation trend, the methylation level of SMAD3 in polyps was between that of normal and tumor tissues." (PMID 33036415, 2020). "The critical role of TGF-β-mediating Smad (mainly Smad3) signaling has been demonstrated in EMT associated with PM2.5 stimulation, bleomycin challenge, and tumour progression/development." (PMID 32655666, 2020). "Our recent work indicated that PJA1 promotes the ubiquitination of SPTBN1 and p-SMAD3, resulting in reduced activity of the tumor-suppressing TGF-β/SMAD3/SPTBN1-dependent pathway in HCC cells." (PMID 33457451, 2020). "TRIB3 has been shown to interact with SMAD family member 3 (SMAD3) to promote transforming growth factor beta (TGFβ)-induced tumor cell migration and invasion." (PMID 33334065, 2020). "It is also hard to reconcile downregulated PCK2 and SMAD3 transcript levels in tumors from diabetic patients with more vigorous tumor propagation seen in T2DM as PCK2 and SMAD3 have been shown to foster tumor growth and dissemination." (PMID 32971867, 2020). "The signaling protein SMAD3 promotes fibroblast proliferation, and induces synthesis and secretion of extracellular matrix proteins including collagen I. SMAD3 is down-regulated in photoaging cells, and is involved in skin photoaging." (PMID 32312940, 2020). "We also demonstrate that α-PD-1 therapy enhances TGFβ-Smad3 signaling within tumor cells, that contributes to EMT." (PMID 30832732, 2019). "The SMAD3 phosphoisoform expression is being used as a surrogate marker for TGF-β signaling activity in tumor tissue in situ and has prognostic significance." (PMID 31817656, 2019). "As with the genes involved in the JAK/STAT3 pathway, 10 mg/kg ajoene extract significantly suppressed the expression of Smad2, Smad3, and Smad4 compared with the tumor control group (Smad2, p = 0.012; Smad3, p = 0.049; Smad4, p < 0.001)." (PMID 31717643, 2019). "We also carried out the analysis of TMEPAI, Smad2 and Smad3 proteins in primary tumor tissues of TNBC." (PMID 31798766, 2019). "Although mechanisms for miR-1224 activity in VEGF signaling and the repression of NOTCH signaling and the TGF-β1/Smad3 signaling pathway have been reported, the role of miR-1224 in tumor biogenesis is unclear." (PMID 31019895, 2019). "For instance, miR‐133a was found to be a tumor suppressive miRNA to inhibit HCC progression through targeting Fos‐related antigen 2 (601575)/transforming growth factor‐β/SMAD family member 3 (603109) signaling pathway." (PMID 31044566, 2019). "The role of SMAD3 in the development of CRC is less understood and somatic tumor mutations in this gene have been observed in only 4.3% of CRC cases." (PMID 31434255, 2019). "HER2 expression pattern is linked with tumor stage and overall survival; the transforming function of HER2 is found more relevant through β‐catenin and SMAD3." (PMID 30714677, 2019). "PI3K/Akt pathway can activate Snai1 and slug expression that has been correlated with EMT and invasive tumor types through repression of E-cadherin and occludin expression mediated by Snai1/SMAD3/SMAD4 complex." (PMID 31798766, 2019). "We observed that areas in the tumor with high nuclear localized phospho-SMAD3 (i.e. high TGFβ activation) also expressed integrin β6, with either antibody." (PMID 30696911, 2019). "In vitro tumor models show that p-ERK is required for TGF-β-induced EMT, and exogenous TGF-β can cause ERK phosphorylation upon SMAD3 phosphorylation." (PMID 31137604, 2019).